AKR1C3 (aldo-keto reductase family 1 member C3)
Diseases named in the same sentence as AKR1C3 in open-access papers (continued):
Sharing a sentence is not in itself a finding about the gene and the disease.
lung carcinoma (5 papers, 2010 to 2025). "Polymorphisms of AKR1C3 have been implicated in susceptibility to various types of cancer, including lung cancer." (PMID 20689807, 2010). "Our analysis also indicated that the three members of the aldo-keto-reductase-1C (AKR1C) family (AKR1C1, AKR1C2, AKR1C3) correlated with resistance to GPX4 inhibitors in lung cancer CLs." (PMID 39995872, 2025). "Furthermore, lung cancer tissues exhibited higher expression levels of PIK3R1, AKR1C3, and EGFR when compared to normal lung tissues." (PMID 39204124, 2024). "Interestingly, it was found that elevated expression of AKR1C3 in lung cancer was restricted to non-small cell lung cancer; no AKRIC3 expression was detected in small cell lung carcinomas (SCLC)." (PMID 25419901, 2014).
ovarian carcinoma (5 papers, 2017 to 2025). A malignant neoplasm originating from the surface ovarian epithelium. "AKR1C3 has been found to be involved in the development of hormone-dependent cancers including breast, prostate, and ovarian cancers." (PMID 40728694, 2025). "AKR1C3 has also been shown to convert androgens to estrogens, influencing hormone signaling and promoting the growth of hormone-dependent cancers, including breast, prostate, and ovarian cancers." (PMID 40728694, 2025). "The aim of this study was to examine expression of AKR1C3 in endometrial and ovarian cancers, and possible correlations between AKR1C3 expression and clinicopathological data, along with evaluation of AKR1C3 as a prognostic biomarker of OS and a predictive biomarker for chemotherapy response." (PMID 33352741, 2020). "In this manner, AKR1C3 can be involved in the pathogenesis of endometrial and ovarian cancers." (PMID 33352741, 2020). "The enzymes that catalyze these reactions (i.e., HSD17B2, AKR1C3, SULT1E1) were detected by immunohistochemistry in ovarian cancer tissue samples." (PMID 28674494, 2017).
acute lymphoblastic leukemia (4 papers, 2022 to 2025). Leukemia with an acute onset, characterized by the presence of lymphoblasts in the bone marrow and the peripheral blood. "In a recent study, 20 normal archival bone marrow samples from patients with B-cell acute lymphoblastic leukemia (ALL) and T-cell ALL were evaluated for AKR1C3 expression by IHC, protein Western blotting, and quantitative reverse-transcriptase PCR." (PMID 37173365, 2023).
acute myocardial infarction (4 papers, 2021 to 2025). Necrosis of the myocardium, as a result of interruption of the blood supply to the area. "Bioinformatics analysis has proven that AKR1C3 serves as a promising biomarker for acute myocardial infarction." (PMID 36035135, 2022). "A recent work suggests that AKR1C3 might be involved in the process of ferroptosis in cardiac myocytes and may act as a bio-marker for Acute Myocardial Infarction (AMI)." (PMID 37288265, 2023).
gastric cancer (4 papers, 2022 to 2024). A primary or metastatic malignant neoplasm involving the stomach. "Indeed, AKR1C3 is associated with several diseases such as prostate cancer, breast cancer, endometrial cancer, cervical cancer, endometriosis, non-small cell lung cancer, colorectal cancer, oropharyngeal tumour, leukaemia, gastric cancer, etc.." (PMID 35208174, 2022). "In this study, we first collected data from several public data portals and clinical samples and systematically analyzed the clinical significance of tissue and plasma AKR1C3 expression in the progression of gastric cancer." (PMID 38577596, 2024). "Overexpression of AKR1C3 is usually observed in connection with the diseases, with the exception of gastric cancer, for which downregulation of mRNA and protein levels were reported." (PMID 35208174, 2022). "Then, to further reveal the clinical significance of dysregulated AKR1C3 expression in gastric cancer, data for 414 GC tissue samples and 36 paired adjacent normal tissue samples were downloaded from the TCGA database, and data for 174 normal tissues were downloaded from the GTEx database." (PMID 38577596, 2024). "In a study led by Frycz and colleagues, the measurement of AKR1C3 transcript and protein levels in non-tumoral and primary tumoral gastric tissues revealed an association with clinicopathological features of gastric cancer (GC)." (PMID 38523637, 2024).
liver cancer (4 papers, 2020 to 2022). An epithelial or non-epithelial malignant neoplasm that arises from the liver. "In contrast, in renal and liver cancers, high AKR1C3 expression was significantly associated with unfavorable prognosis." (PMID 33352741, 2020). "Meanwhile, the MTT and cell colony-forming assays showed that AKR1C3 knockdown can significantly suppress the proliferation of liver cancer cells treated with 10 μM sorafenib for 48 h." (PMID 35359392, 2022). "In our experiments, downregulation of AKR1C3 restrained cell proliferation and increased the sensitivity of liver cancer cells to sorafenib, and upregulation of AKR1C3 increased cell proliferation in HCC cells." (PMID 35359392, 2022). "We found that knockouts of AKR1C3 or TPX2 can significantly inhibit the invasion of liver cancer cells." (PMID 36686655, 2022). "It was found that compared with control, the overexpression of AKR1C3 increased liver cancer cell proliferation using the MTT assay." (PMID 35359392, 2022). "Together, these findings demonstrate that knockdown of AKR1C3 in liver cancer cells induced sensitivity toward sorafenib treatment." (PMID 35359392, 2022). "A violin plot shows that the expression of AKR1C3, NQO1, TEK and TPX2 was significantly associated with different disease states (normal, cirrhosis or liver cancer) (p < .05) (GSE54238)." (PMID 36686655, 2022). "Through bioinformatics analysis, our study found the relationship between AKR1C3 and sorafenib resistance and further proved that AKR1C3 downregulation can significantly increase the sensitivity of liver cancer cells to sorafenib." (PMID 35359392, 2022). "And the knockouts of AKR1C3 or TPX2 can significantly inhibit the invasion of liver cancer cells." (PMID 36686655, 2022). "We further explored the impact of AKR1C3 or TPX2 on the development of liver cancer in vitro." (PMID 36686655, 2022). "The results indicated that there was no significant change in the expression of total AKT, when AKR1C3 was overexpressed in liver cancer cells, while that of p-AKT was upregulated significantly in overexpressed AKR1C3 cells and in AKR1C3 overexpression cells with 10 μM sorafenib." (PMID 35359392, 2022). "In addition, GEPIA online analysis showed that ESR1, AR, CCNB1, CDK1, AKR1C3 and CCNA2 might become potential target genes for the survival and prognosis of PADP for the treatment of liver cancer." (PMID 35463358, 2022).
lung adenocarcinoma (4 papers, 2020 to 2024). A carcinoma that arises from the lung and is characterized by the presence of malignant glandular epithelial cells. "Identified as a specific AKR1C3 inhibitor, it restored cytotoxicity to daunorubicin and idarubicin in the lung adenocarcinoma A549 cell line with high endogenous expression of AKR1C3." (PMID 38523637, 2024). "After confirming that the inhibition of AKR1C3 remains beyond the synergy between DAUN and ZAN in transfected cells, combination studies were performed with the lung adenocarcinoma cell line A549, which naturally expresses considerable amounts of AKR1C3." (PMID 36297430, 2022). "The expression of AKR1C1, AKR1C2, AKR1C3, and AKR1C4 proteins, which was mainly overexpressed in lung adenocarcinoma (A549) cells and associated with drug resistance in NSCLC, was found in the A549 CD166 + EpCAM + CSC subpopulation." (PMID 33670440, 2021).
prostate tumors (4 papers, 2009 to 2023). "We found high expression levels of AKR1C3 in a sub-group of PC bone metastases, which confirm results previously reported in castration-resistant primary prostate tumors and CRPC tissue of different metastatic origin." (PMID 24244276, 2013). "Furthermore, immunohistochemical analysis confirmed the upregulation of AKR1C3 protein in prostate tumours relative to normal tissue." (PMID 20003443, 2009). "As observed in prostate tumours, AKR1C3 is commonly over-expressed in malignant breast tissues." (PMID 20003443, 2009). "The Aldo-Keto reductase family members (AKR1C1, AKR1C3, AKR1C4, and AKR1C8P) AKR1C1 and AKR1C3 were among the highest upregulated genes in our OC2 network, and their expression increases with disease progression in prostate tumors (left)." (PMID 37484909, 2023). "We however found high expression levels of certain steroidogenic enzymes; SRD5A1, AKR1C2, AKR1C3, and HSD17B10, in bone metastases when compared to non-malignant prostate and primary prostate tumor tissue." (PMID 24244276, 2013).
cervical cancer (3 papers, 2013 to 2024). A primary or metastatic malignant neoplasm involving the cervix. "Conversely, AKR1C3 silencing upregulated LCN2 expression, resulting in decreased cell migration, invasion, and cytoskeleton changes in cervical cancer cells." (PMID 38523637, 2024). "The second most downregulated gene was aldo-keto reductase family 1, member C3 (AKR1C3), which has been reported to be overexpressed in several cancers, and to increase the migration and invasion of cervical cancer cells and to change the organization of their cytoskeleton." (PMID 26918341, 2016).
glioblastoma (3 papers, 2011 to 2026). The most malignant astrocytic tumor (WHO grade IV). "In addition, the results showed that AKR1B1, AKR1C2, and AKR1C3, which were also members of the aldosterone reductase family, were also involved in the mechanism of the resistance of glioblastoma to adriamycin." (PMID 37173953, 2023).
pancreatic cancer (3 papers, 2020 to 2023). "AKR1C3 is overexpressed in 90% of hepatocellular tumors and in 50% of pancreatic tumors, and there is a significant unmet need for better treatments in these cancers, especially for patients whose disease has progressed after surgery and/or systemic chemotherapy." (PMID 37173365, 2023).
polycystic ovary syndrome (3 papers, 2017 to 2022). A disorder that manifests as multiple cysts on the ovaries. "Since it has been reported that the function of AKR1C3 is associated with lipid metabolism and lipogenesis in adipocytes of patients with polycystic ovary syndrome (PCOS) 28, we decided to investigate the role of this gene in lipid metabolism in HCC." (PMID 36451864, 2022). "Recent studies of healthy normal-weight women with NIH-defined PCOS show enhanced AKR1C3 activity in SC abdominal adipose favoring lipid storage in combination with preferential intra-abdominal fat deposition accompanying hyperandrogenemia and low-normal insulin sensitivity." (PMID 35012577, 2022).
psoriasis (3 papers, 2016 to 2023). An autoimmune condition characterized by red, well-delineated plaques with silvery scales that are usually on the extensor surfaces and scalp. "To explore the association between reduced AKR1C3 expression and the development of psoriasis, we focused on single nucleotide polymorphisms (SNPs) of AKR1C3." (PMID 36841845, 2023). "We found that rs12529 G > C and rs12387 A > G SNPs in AKR1C3, an enzyme involved in prostaglandin metabolism and keratinocyte differentiation, are more common in female psoriasis patients with early disease onset and may be associated with severe disease." (PMID 36841845, 2023). "Abnormal early differentiation of epidermal keratinocytes associated with reduced expression of AKR1C3 may be one aspect of the pathogenesis of psoriasis." (PMID 36841845, 2023). "We investigated whether single nucleotide polymorphisms (SNPs) in AKR1C3 are associated with the pathogenesis of psoriasis." (PMID 36841845, 2023). "In the psoriasis lesional skin, the expression of AKR1C3 was significantly downregulated compared with that in healthy normal skin and non-lesional skin." (PMID 36841845, 2023). "These SNPs downregulate AKR1C3 expression in the psoriasis lesional epidermis and impair keratinocyte AKR1C3-mediated regulation of keratinization." (PMID 36841845, 2023). "In conclusion, AKR1C3 downregulation caused by rs12529 G > C and rs12387 A > G SNPs in the epidermis induces abnormal early differentiation of keratinocytes and skin barrier dysfunction, which may contribute to the genetic pathogenesis of psoriasis in young females." (PMID 36841845, 2023). "Although the number of AKR1C3 SNPs in this cohort is unknown, keratinocyte differentiation was clearly abnormal in the psoriasis lesional skin." (PMID 36841845, 2023).
Alzheimer disease (2 papers, 2023 to 2026). A progressive, neurodegenerative disease characterized by loss of function and death of nerve cells in several areas of the brain leading to loss of cognitive function such as memory and language. "Dysregulation of AKR1C2 and AKR1C3 has been observed in Alzheimer’s disease, suggesting their potential role in disease progression." (PMID 37965040, 2023).
astrocytoma (2 papers, 2017 to 2024). "Moreover, high expression of 7 of the high-malignant genes (C7ORF46, DUSP4, HS3ST3B1, ODZ1, TTL, VAV3, ZDHHC23) or low expression of 4 of the low-malignant genes (AKR1C3, ARHGEF10L, SMAD7, ST3GAL6) was associated with a lower progression free survival probability of grade III astrocytoma patients." (PMID 29152145, 2017).
COVID-19 (2 papers, 2021 to 2023). A disease caused by infection with severe acute respiratory syndrome coronavirus 2. "In addition, AKR1C3 activity or quantification must be evaluated in further studies in order to clarify its role in COVID-19." (PMID 37237997, 2023).
lung squamous cell carcinoma (2 papers, 2015 to 2022). "Positive immunoreactivity AKR1C3 was widely present in both adenocarcinoma and squamous cell carcinoma of the lung and gastroesophageal junction." (PMID 24934327, 2015). "The results showed that AKR1C3 was mainly highly expressed in cholangiocarcinoma (CHOL), kidney renal clear cell carcinoma (KIRC), liver hepatocellular carcinoma (LIHC) and lung squamous cell carcinoma (LUSC)." (PMID 36276091, 2022).
lymph node metastases (2 papers, 2015 to 2020). "Expression of AKR1C3 may be used for the prediction of lymph node metastasis in CRC." (PMID 33294000, 2020).
lymphoma (2 papers, 2022). A malignant (clonal) proliferation of B- lymphocytes or T- lymphocytes which involves the lymph nodes, bone marrow and/or extranodal sites. "There are several lines of evidence regarding the role of AKR1C3 and ABC transporters in aggressive lymphomas and their sensitivity to ANT therapy, identifying them as potential drug targets." (PMID 36297430, 2022).
myeloid leukemia (2 papers, 2012 to 2024). A clonal proliferation of myeloid cells and their precursors in the bone marrow, peripheral blood, and spleen. "Activating polymorphisms of the AKR1C3 gene has been associated with an increased chance of developing childhood myeloid leukaemia, and increased expression of AKR1C3 has been observed in a patient with myelodysplastic syndrome who went on to develop AML-M2." (PMID 23213553, 2012). "Research indicates that reduced expression of AKR1C3 prevents the proliferation of human myeloid leukemia cells." (PMID 39596349, 2024). "As to this possible mode of action of AKR1C3, again inhibiting enzyme activity is important for increasing the sensitivity of myeloid leukemia cells to ATRA." (PMID 23213553, 2012).
neuroblastoma (2 papers, 2015 to 2024). Neuroblastoma (NB) is the most common solid, extracranial childhood tumor. "However, recent studies demonstrated that AKR1B and AKR1C3 are highly expressed in many human cancers including prostate, neuroblastoma and lung and they are crucial to regulate cell differentiation and cancer cell proliferation as well as to mediate drug resistance." (PMID 39185122, 2024).
renal carcinoma (2 papers, 2014 to 2017). A carcinoma arising from the epithelium of the renal parenchyma or the renal pelvis. "Increased expression of proteins involved in sex steroid inactivation (AKR1C1, AKR1C2, AKR1C3, AKR1B10) in DIO1 re-expressing renal cancer cells might indicate decreased local production of androgens, which have been linked to proliferation of renal and other cancers expressing androgen receptor." (PMID 29272308, 2017).
sarcoidosis (2 papers, 2020 to 2023). Sarcoidosis is a multisystemic disorder of unknown cause characterized by the formation of immune granulomas in involved organs. "According to Gini score calculated from gene expression values, we examined the top-6 most important AA metabolism-related genes (including PLA2G6, PLA2G7, AKR1C1, AKR1C3, LTA4H, and PTGER4) in sarcoidosis, whose expression showed a positive correlation with sarcoidosis samples." (PMID 33097805, 2020).
schizophrenia (2 papers, 2021 to 2024). A major psychotic disorder characterized by abnormalities in the perception or expression of reality. "This could also be relevant to the pathophysiology of schizophrenia because AKR1C3 also functions as prostaglandin (PG) F2α synthase, with PGF2α and its highly active metabolite 8-iso-PGF2α promoting oxidative stress and contributing to the inflammatory environment." (PMID 39201417, 2024). "Thus, the suppressed AKR1C3 function in patients suggested by our results could be involved in counterregulatory mechanisms that may alleviate the oxidative stress and inflammation that often accompany schizophrenia." (PMID 39201417, 2024).
acne (1 paper, 2023). An inflammatory process of the sebaceous glands which is characterized by comedones, nodules, papules and/or pustules on the skin. "More importantly, a significant difference between HA-P5 and the commercial FGFR inhibitor AZD4547 is that HA-P5 does not trigger the overexpression of aldo-keto reductase family 1 member C3 (AKR1C3), which blocks acne treatment by catalyzing the synthesis of testosterone." (PMID 36803994, 2023). "Since AKR1C3 encodes an enzyme for the synthesis of androgen, the elevation of AKR1C3 enhances AR signalling, which is not conducive to treating acne." (PMID 36803994, 2023). "Moreover, unlike AZD4547, HA-P5 does not trigger the overexpression of an obstacle gene for acne therapy, namely, AKR1C3, and exhibits stronger antiacne activities." (PMID 36803994, 2023).
astroglioma (1 paper, 2022). "AKR1C1 and AKR1C3 are members of the AKR superfamily which has been previously shown to be associated with oncogenic potential and proliferation capacity, and selective targeting of AKR1C proteins in GBM could delay the acquisition of resistance to TMZ of astroglioma cells." (PMID 35359663, 2022).
atherosclerosis (1 paper, 2025). A disease characterized by the build-up of fatty material and calcium deposition in the arterial wall resulting in partial or complete occlusion of the arterial lumen. "The expression of other key atherosclerosis-related enzymes, including cytochrome P450 8B1 (CYP8B1) and lanosterol synthase (LSS), was downregulated, whereas the expression of cyclooxygenase 2 (COX-2) and aldo–keto reductase family 1 member C3 (AKR1C3) was induced by PFOS and PFOA." (PMID 40728694, 2025).
atopic dermatitis (1 paper, 2022). "The steroidogenic enzyme AKR1C3 plays an important role in many diseases, such as prostaglandin disorder, metastatic breast tumors and atopic dermatitis." (PMID 36505054, 2022).
benign prostatic hyperplasia (1 paper, 2014). A non-cancerous nodular enlargement of the prostate gland. "Low immunoreactivity of AKR1C3 was detected in normal prostate epithelium, benign prostatic hyperplasia (BPH) and prostatic intraepithelial neoplasia (PIN)." (PMID 24571686, 2014).
bone tumors (1 paper, 2019). "Enzalutamide treatment resulting in suppression of AKR1C3 and HSD3B1/2 in tumor cells leads to inhibition of bone tumor growth." (PMID 31638934, 2019). "Bone tumor analysis shows that ERG knockdown results in diminished expression of AKR1C3 and HSD3B1 in bone tumors." (PMID 31638934, 2019). "To determine enzalutamide responsiveness is related to androgen synthesis in bone tumors, we evaluated the expression of key enzymes in androgen synthesis, AKR1C3, HSD3B1 and HSD3B2, in bone tumors." (PMID 31638934, 2019).